JAG2 (jagged canonical Notch ligand 2)
Description:
Putative Notch ligand involved in the mediation of Notch signaling. Involved in limb development (By similarity).
Synonyms: hJ2; LGMDR27; SER2
Tractability: Antibody: its Gene Ontology location is reachable by antibodies, with high confidence; UniProt predicts a signal peptide or a membrane-spanning region.
Gene: Protein-coding gene on chromosome 14 (105,140,982 to 105,168,919, reverse strand). Ensembl gene ENSG00000184916.
Subcellular location: Membrane
Subcellular location (Human Protein Atlas): Vesicles
Pathways (Reactome):
Disease: Constitutive Signaling by NOTCH1 HD Domain Mutants; Constitutive Signaling by NOTCH1 HD+PEST Domain Mutants; Constitutive Signaling by NOTCH1 PEST Domain Mutants; Constitutive Signaling by NOTCH1 t(7;9)(NOTCH1:M1580_K2555) Translocation Mutant
Signal Transduction: Activated NOTCH1 Transmits Signal to the Nucleus; NOTCH2 Activation and Transmission of Signal to the Nucleus; NOTCH3 Activation and Transmission of Signal to the Nucleus
Gene Ontology:
Molecular function: growth factor activity; Notch binding; protein binding; calcium ion binding
Biological process: cell differentiation; regulation of cell population proliferation; spermatogenesis; T cell differentiation; thymic T cell selection; auditory receptor cell fate commitment; Notch signaling pathway; positive regulation of Notch signaling pathway; cell communication; gamma-delta T cell differentiation
Cellular component: plasma membrane; membrane
Genetic constraint (gnomAD): Loss-of-function variants: 45 observed, 116.56 expected, observed/expected ratio (o/e) 0.39, 90% interval 0.3 to 0.5. The synonymous counts are far from expectation, so gnomAD's model fits this gene poorly and the ratio says little. Missense variants: 1,449 observed, 1,641.1 expected, observed/expected ratio (o/e) 0.88, 90% interval 0.85 to 0.92. Synonymous variants: 838 observed, 680.88 expected, observed/expected ratio (o/e) 1.23, 90% interval 1.16 to 1.3.
Gene-disease validity (ClinGen):
ClinGen rates the evidence that JAG2 causes each of these diseases.
autosomal recessive limb-girdle muscular dystrophy (autosomal recessive): Moderate. Autosomal recessive form of limb-girdle muscular dystrophy.
Homologues: Orthologues: rat Jag2 (91% identical), mouse Jag2 (90% identical), pig JAG2 (90% identical), macaque JAG2 (88% identical), dog JAG2 (86% identical), chimpanzee JAG2 (77% identical), guinea pig JAG2 (73% identical), tropical clawed frog jag2 (63% identical), zebrafish jag2b (59% identical), zebrafish jag1b (51% identical), zebrafish jag1a (50% identical), Drosophila melanogaster Ser (22% identical), and 3 more. Paralogues in human: JAG1 (53% identical), NOTCH4 (29% identical), DLL1 (22% identical), DLL4 (20% identical), DNER (14% identical).
Diseases named in the same sentence as JAG2 in open-access papers:
JAG2 is named in the same sentence as 100 diseases in open-access papers, as found by Europe PMC text mining. Sharing a sentence is not in itself a finding about the gene and the disease. The quoted sentences say what the papers report.
colorectal cancer (19 papers, 2017 to 2025). A primary or metastatic malignant neoplasm that affects the colon or rectum. "Mechanistic investigations indicated that the Notch ligand JAG2 was a direct target of tRF/miR-1280 binding and that tRF/miR-1280 inhibited colorectal cancer growth and metastasis by suppressing the Notch signaling pathway that supported the CSC phenotype." (PMID 35186731, 2022). "Subsequent studies have reported that tRF/miR-1280 inhibits stem-like cells and metastasis in colorectal cancer by targeting JAG2." (PMID 36388094, 2022). "For example, tRNALeu-derived tRF promoted cancer cell proliferation and invasion by inhibiting JAG2 in a miRNA-like manner in colorectal cancer cell lines." (PMID 36230476, 2022). "In colorectal cancer, tRF/miR-1280 can inhibit cell proliferation and tumour growth by targeting Jagged 2 (JAG2) and inhibiting the Notch signal transduction pathway." (PMID 34341710, 2021). "One of Notch ligand, JAG2 appeared to exert several carcinogenesis, endometrial cancer, colorectal cancer., myeloma., pancreatic cancer, and breast cancer." (PMID 32250571, 2020). "Similar to the findings in tissues, the expression of both JAG2 mRNA and protein was significantly increased in the colorectal cancer cell lines compared with that of normal colorectal cell line CCD18-Co." (PMID 31198409, 2019). "It was found in our previous studies that JAG2 was abnormally and highly expressed in colorectal cancer cells and that the expression level of JAG2 was positively correlated with the migration and invasion ability of colorectal cancer cells." (PMID 31198409, 2019). "This study further explored the specific mechanism by which JAG2 promotes migration and invasion of colorectal cancer cells." (PMID 31198409, 2019). "In summary, we revealed the unusual and interesting biological functions of JAG2 in colorectal cancer cells." (PMID 31198409, 2019). "QPCR and Western Blot were used to analyze the differential expression of JAG2 mRNA and protein between normal human colon tissue cells and various colorectal cancer cells." (PMID 31198409, 2019). "JAG2 mRNA expression in different clinical stages of colorectal cancer and normal intestinal tissues was detected by quantitative PCR (QPCR)." (PMID 31198409, 2019). "Similar to the findings in tissues, the expression of both JAG2 mRNA and protein was significantly increased in these colorectal cancer cell lines compared with that of the CCD18-Co." (PMID 31198409, 2019). "When JAG2 was overexpressed in colorectal cancer cell line HT29, PRAF2 was up-regulated, then the number of exosomes secreted by colorectal cancer cells was significantly increased and the level of JAG2 and PRAF2 proteins in exosomes was upregulated." (PMID 31198409, 2019). "Co-expressed genes of JAG2 in colorectal cancer cells were identified using siRNA and transcriptome microarray technology." (PMID 31198409, 2019). "Jag2 was the most frequently observed ligand that was overexpressed in 52%, while a higher expression of Jag1, Dll1, Dll3, and Dll4 was found in 26%, 25%, 25%, and 39% colorectal cancers, respectively." (PMID 32211044, 2020). "Several investigations indicate that overexpression of Notch1, Jag1, and Jag2 was found in human intestinal adenomas, implying that elevated Notch signaling might be responsible for colorectal cancer initiation." (PMID 32211044, 2020). "First, the expression of JAG2 in colorectal cancer tissues was confirmed." (PMID 31198409, 2019). "Few studies on the function and mechanism of JAG2 in colorectal cancer have been reported to date." (PMID 31198409, 2019). "JAG2 was abnormally expressed in colorectal cancer tissues and directly related to clinical stages." (PMID 31198409, 2019). "Further analysis revealed the co-expression of JAG2 with PRAF2 in colorectal cancer cells." (PMID 31198409, 2019).
colorectal cancer (continued). "In addition to JAG1 and DLL4, the JAG2/NOTCH pathway also exerts a cancer-promoting effect in colorectal cancer cells, as JAG2 knockdown in colorectal cancer cells inhibits their expression of CD133, decreasing in a similar manner their ability to form spheroids and to induce metastasis." (PMID 37860822, 2023). "Notably, tRF/miR-1280 can reduce the proliferation and colony formation of patient-derived colorectal cancer cells by directly targeting the ligand JAG2 in the Notch pathway, indicating that the Notch signalling pathway is involved in the regulation of colorectal cancer cells." (PMID 34341710, 2021). "The tRF/miR-1280 derived from tRNALeu and pre-miRNA inhibits Notch signaling pathway by directly targeting Notch ligand JAG2 mRNA 3′ UTR, inhibiting the growth and metastasis of colorectal cancer cells." (PMID 34537070, 2021). "JAG2-rich exosomes were released from colorectal cancer cells in a PRAF2-dependent way, while these exosomes regulated the metastasis of colorectal cancer cells in a paracrine manner." (PMID 31198409, 2019). "Co-expression of JAG2 and EMT markers was randomly detected in 6 specimens of N1/N2 colorectal cancer tissues." (PMID 31198409, 2019). "Next, the differential expression of JAG2 in normal colorectal cell line CCD18-Co and colorectal cancer cell lines (RKO, HT29, HCT116, SW620, SW480 and DLD-1) was then compared." (PMID 31198409, 2019). "Data from the present study revealed that the ability of JAG2 to promote the migration of colorectal cancer cells was independent of the EMT and the canonical Notch signaling pathway." (PMID 31198409, 2019). "In addition, tRF/miR-1280 was reported to inhibits the Notch/Gata signaling pathway by directly interacting with the JAG2 3’ UTR, and simultaneously upregulates miR-200b expression, thereby inhibit the EMT and extracellular matrix degradation of colorectal cancer." (PMID 36797764, 2023). "A study conducted on colorectal cancer cells showcased that a tRF derived from tRNALeu functions as miRNAs and inhibits the Notch pathway by interacting with the 3’UTR of Notch ligand jagged 2 (JAG2) mRNA, and suppresses cancer stem-like cells in colorectal cancer progress." (PMID 35574338, 2022). "Our previous studies showed that JAG2 was highly expressed in colorectal cancer cells and the migration and invasion ability, rather than the proliferation ability, of the cells was affected by the altered relative expression level of JAG2." (PMID 31198409, 2019). "This is the evidence supporting the biological function of JAG2 through non-canonical Notch and non-EMT-dependent pathways and also the first demonstration of the functions of PRAF2 in colorectal cancer cells." (PMID 31198409, 2019).
breast cancer (18 papers, 2009 to 2025). A primary or metastatic malignant neoplasm involving the breast. "Jag2 has been associated with adenomas, pancreatic and breast cancer, Rpl37a with nasopharyngeal carcinoma cell lines, and the rest with glioblastoma." (PMID 21649900, 2011). "Mechanistically, the hypoxia-Jag2-Notch1 axis between breast cancer cells and bone marrow stromal cells was shown to be important for metastasis and for the enrichment of BCSCs." (PMID 38269089, 2023). "JAG2 expression significantly correlates with angiogenic processes and vascular development in breast cancer, and is induced at the transcriptional level in hypoxic tumor cells." (PMID 33842346, 2021). "In clinical breast cancer samples, both JAG2 and Notch signaling is upregulated at the hypoxic invasion front and JAG2 is correlated with metastasis-free survival of breast cancer patients." (PMID 34374886, 2021). "Interestingly, coculturing of Jag2-expressing bone marrow stromal cells with breast cancer cells led to increase in Notch reporter activity only under hypoxic condition, indicating the role of Jag2-expressing hypoxic stroma in cancer cell Notch activation." (PMID 38269089, 2023). "Activation by hypoxia of another Notch ligand, JAG2, is also correlated with metastasis-free survival of breast cancer patients, and may be a valuable prognostic marker for metastatic breast cancer." (PMID 34374886, 2021). "In addition to OSCC, JAG2 is overexpressed in many malignant tumors, including myeloma, pancreatic cancer, and breast cancer." (PMID 32250571, 2020). "The co-culture of ER+ breast cancer cells with obese ASCs activated many pathways such as leptin, IL6, Notch, and jagged canonical Notch ligand 2 (JAG2), which mediated radiation resistance in ER+ breast cancer cells." (PMID 36010901, 2022). "IHC in breast cancer patient samples revealed the upregulation of NICD1 and Jag2 in the invasive front rather than within the core of the tumor, suggesting Jag2 mediated Notch1 activation playing a role in breast cancer invasion and metastasis." (PMID 38269089, 2023). "Although its expression is strongly upregulated at the hypoxic invasive front in breast cancers samples, we did not observe significant difference in the expression levels of the new JAG2 transcript in BC cells vs. non-tumoral cell line." (PMID 26784191, 2016).
myeloma (12 papers, 2010 to 2025). "The NOTCH ligands JAG1 and JAG2 have been correlated in vitro with multiple myeloma (MM) cell proliferation, drug resistance, self-renewal and a pathological crosstalk with the tumor microenvironment resulting in angiogenesis and osteoclastogenesis." (PMID 37834003, 2023). "To gain insight into the clinical relevance of JAG1 and JAG2 expression, we analyzed primary MM patient profiles, from the publicly available Multiple Myeloma Research Foundation (MMRF) CoMMpass database." (PMID 37834003, 2023). "Jagged2 (Jag2) was identified as a ligand of Notch receptor in multiple myeloma patient origin specimens." (PMID 35574466, 2022). "JAG2 has been found to be overexpressed in malignant plasma cells from multiple myeloma patients and cell lines." (PMID 34395276, 2021). "Moreover, arsenic trioxide inhibits JAG2 expression, thus impairing myeloma cell growth (Hu, Huang, Hong, Lu, & Zhu, 2013)." (PMID 32250571, 2020). "Data from the real-time PCR assay showed that the mRNA expression levels of the Jag2 gene and its downstream gene Hes1 were both significantly down-regulated after the myeloma cells were treated with ATO while the expression of the tumor suppressor gene PTEN was up-regulated." (PMID 23497375, 2013). "On the other hand, cancers in which over-expression of Jag1, Jag2, and DLL1 are associated with poor survival, such as prostate and breast carcinomas, CNS tumors, and multiple myeloma, may be tractable targets." (PMID 20161710, 2010). "In conclusion, our findings advocate for JAG2 as a predictive marker for adverse prognosis in MM, and both JAG ligands emerge as potential targets for anti-myeloma therapy." (PMID 37834003, 2023). "Representative images and correlation analyses of the percentage of MM cells and JAG1, JAG2, HES6 in MM cells, and HES6 in NM non-myeloma cells are reported here." (PMID 37834003, 2023). "Thus, Jag2 might be a new therapeutic target for myeloma treatment." (PMID 23497375, 2013). "The results of these analyses revealed statistically significant positive correlations between the percentage of MM cells in the BMBs, the expression of both JAG1 and JAG2, and the activation of NOTCH signaling in myeloma (HES6 MM) as well as in non-myeloma cells (HES6 NM)." (PMID 37834003, 2023).
ovarian carcinoma (11 papers, 2005 to 2024). A malignant neoplasm originating from the surface ovarian epithelium. "One study reported upregulation of the Notch3 gene in all analyzed ovarian cancers, while the second study reported increased Jag2 gene expression in ovarian cancer cell lines compared with benign controls." (PMID 25366565, 2014). "In ovarian cancer, CXCL8 can recruit TANs in TME and induce the expression of Jagged2 (JAG2) in TANs which subsequently inhibit the activity of CD8(+) T cells." (PMID 35372515, 2022).
lung adenocarcinoma (7 papers, 2014 to 2025). A carcinoma that arises from the lung and is characterized by the presence of malignant glandular epithelial cells. "It has been reported that in mice, JAG2 is associated with the promotion of metastasis in lung adenocarcinoma." (PMID 31217907, 2019). "The expression of JAG2 on the surface of lung adenocarcinoma cells triggers the interaction with Notch receptors and promotes the metastatic potential of these LUAD stem cells." (PMID 40943414, 2025). "We previously reported that JAG2, a Notch ligand, promotes lung adenocarcinoma metastasis by suppressing miR-200, which is mediated by GATA3." (PMID 26395571, 2015). "In addition, we integrated BMP4 into the JAG/Notch signaling pathway and proposed a regulatory loop consisting of JAG2, GATA3, miR-200, and BMP4, suggesting that BMP4 interconnects with various cell signaling partners to induce tumorigenesis and metastasis in lung adenocarcinomas." (PMID 26395571, 2015).
bladder cancer (6 papers, 2016 to 2023). "In contrast, JAG2 expression is associated with a poor prognosis in patients with hepatocellular carcinoma and urinary bladder cancer." (PMID 32250571, 2020). "Chen el al. showed that the NOTCH/JAG2 signaling pathway plays an important role in the regulation of bladder cancer cell proliferation, growth, and invasion processes, thus demonstrating that JAG2 expression is involved in cancer progression." (PMID 35136410, 2022). "The result showed that iG2 strongly inhibited the expression of Hh pathway transcriptional factors Gli1 and Gli2, as well as the downstream protein Jag2 in primary bladder cancer cells." (PMID 27465044, 2016). "The iG2 can strongly downregulated the expression of Gli1, Gli2, and downstream Jag2 genes in bladder cancer cells." (PMID 27465044, 2016). "Although it has been reported that up regulation of JAG2 expression was associated with the progression of tumour including in pancreatic, lung and bladder cancer, the role of JAG2 in cancer remains unclear." (PMID 30679934, 2019).
colon cancer (6 papers, 2019 to 2025). "It has been shown that JAG2 acts as a prognostic factor for colon cancer and is involved in regulating colon cancer cell migration and invasion." (PMID 36439446, 2022). "The expression levels of INHBA and JAG2 in colonic cancer cell lines (CACO-2, HT29, SW480 and HCT116) were significantly higher than that in colonic epithelial cell line (NCM460)." (PMID 34103052, 2021). "In order to verify the reliability and accuracy of our results, we identified the expression levels of INHBA and JAG2 in CCa tumor tissues, adjacent tissues, human colonic epithelial cell line and colonic cancer cell lines." (PMID 34103052, 2021). "The expression levels of INHBA and JAG2 in colonic epithelial cell line were remarkably lower than that in colonic cancer cell lines." (PMID 34103052, 2021). "Downregulation of ENST00000455974 results in proliferation inhibition of colon cancer cells via the suppression of JAG2." (PMID 33246471, 2020). "Inhibition of ENST00000455974 causes disrupts the migration of colon cancer cells, whereas ENST00000455974 upregulation enhances the metastasis of colon cancer via the upregulation of JAG2." (PMID 33246471, 2020). "Moreover, the knockdown of JAG2 sensitized colon cancer cells to oxaliplatin by enhancing apoptotic cell death." (PMID 34680255, 2021). "Our experimental results reveal for the first time that PRAF2 overexpression could increase the secretion of colon cancer cell exosomes, and promote the migration and invasion of tumor cells in a JAG2-dependent manner through signal transduction in the microenvironment." (PMID 31198409, 2019). "Co-expression status of JAG2 and epithelial–mesenchymal transition (EMT) markers in colon cancer tissues and cells was analyzed." (PMID 31198409, 2019). "Jag2 promotes colon cancer cell migration and invasion through a non-EMT pathway independent of the canonical Notch signaling pathway." (PMID 41315239, 2025). "Our previous studies revealed that Jagged 2 (JAG2) is involved in the regulation of migration and invasion of colon cancer cells without affecting cell proliferation." (PMID 31198409, 2019). "More interestingly, JAG2 also promoted the migration and invasion of colon cancer cells in a non-EMT pathway." (PMID 31198409, 2019).